PON1 (paraoxonase 1)
Diseases named in the same sentence as PON1 in open-access papers (continued):
Sharing a sentence is not in itself a finding about the gene and the disease.
heart failure (15 papers, 2011 to 2026). Inability of the heart to pump blood at an adequate rate to meet tissue metabolic requirements. "Materials and Methods: A targeted literature search was conducted using Scopus, PubMed, and Google Scholar to identify studies examining the diagnostic and prognostic value of TN and PON1 in heart failure (HF)." (PMID 41752683, 2026). "This indicates that the median levels of both biomarkers are not equal across the three groups, suggesting a potential association between TETRA and PON1 levels and the severity of heart failure." (PMID 40422267, 2025). "Significant decreases in PON-1 activity throughout the follow-up were also linked with an increased risk of adverse heart failure outcomes." (PMID 36140402, 2022). "After a follow-up of 2.8 years, decreased PON-1 activity was found to be linked with an increased risk of poor heart failure outcomes after adjustment for possible risk factors." (PMID 36140402, 2022). "Similarly, Hammadah (2017) found that reduced baseline PON1 activity and decreased levels over time were associated with adverse outcomes in heart failure patients, supporting our observation of lower PON1 levels in those with more severe heart failure." (PMID 40422267, 2025). "Furthermore, PON1 is involved in innate immunity and the modulation of inflammation, both of which are implicated in the pathogenesis of heart failure." (PMID 40422267, 2025). "In a previous study, an increase in oxidative stress and production of ROS in different stages of heart failure (according to NYHA classification) were associated with decreasing PON-1 activity, that is, as disease severity increased, serum PON-1 activity decreased gradually in dogs with CHF." (PMID 35203200, 2022). "Our findings contribute to a growing body of evidence supporting the roles of tetranectin and paraoxonase 1 in heart failure." (PMID 40422267, 2025). "Given its protective effects against oxidative stress and inflammation, PON1 has been investigated as a potential biomarker for various cardiovascular diseases, including coronary artery disease and heart failure." (PMID 40422267, 2025). "Firstly, we found that both TETRA and PON1 levels decrease in a stepwise manner as heart failure worsens." (PMID 40422267, 2025). "The observed decrease in both TETRA and PON1 levels with increasing heart failure severity aligns with previous reports." (PMID 40422267, 2025). "In contrast to specific cardiac biomarkers (cTnI and NT-proBNP), which appear to have significant correlation with the stage of heart failure in degenerative valvular disease, PON-1 does nοt appear to share validity." (PMID 36669034, 2023). "Similarly to TETRA, pairwise comparisons using the Mann–Whitney U test with a Bonferroni correction (adjusted alpha = 0.0167) revealed a stepwise decrease in PON1 levels with increasing heart failure severity." (PMID 40422267, 2025). "The major protein componentof HDL-C is apolipoprotein (Apo) A-I, while paraoxonase-1 (PON-1) is an essentialmediator for many protective functions of HDL, and HDL may act through componentslike (Apo) A-I or PON-1 to delay heart failure progress." (PMID 39076447, 2023). "Non-specific changes in PON-1 activity can be observed by the systemic inflammation caused by advanced heart failure, and possibly also by liver congestion in stage C and D dogs." (PMID 36669034, 2023). "However, the aim of the study was to assess oxidative stress, as indicated by PON-1 activity, between heart failure stages." (PMID 36669034, 2023). "These discoveries indicate that PON-1 activity might indeed serve as a prognostic biomarker in heart failure." (PMID 36140402, 2022). "In contrast, expression levels of paraoxonase enzymes 1-3 (Pon1, Pon2, Pon3), which could detoxify oxidated lipids and alleviate angiotensin-II-induced heart failure, were unaltered in Tg-SCD hearts (Figure A6a–c)." (PMID 34576047, 2021).
heart failure (continued). "However, the PON1 activity level was lower in the heart failure patients compared with the controls." (PMID 28038449, 2017). "Secondly, we observed a strong positive correlation between TETRA and PON1 levels, but only in patients without heart failure." (PMID 40422267, 2025). "N-terminal-prohormone-B-type natriuretic peptide concentration was expectedly correlated with clinical stage and echocardiographic indices of cardiomegaly and heart failure, but not with Paraoxonase-1 activity." (PMID 36669034, 2023). "The minor differences between the subclinical stages of the dogs in our study indicate that if oxidative stress eventually plays an important role in the progression of heart failure, PON-1 activity does not appear to be a reliable marker." (PMID 36669034, 2023). "Activities of some antioxidant enzymes such as paraoxonase-1 (PON-1) in serum and manganese superoxide dismutase (MnSOD) in the myocardium, if not all enzymes, are diminished in patients with heart failure." (PMID 26791643, 2011). "The decrease in PON1 in dogs at stage D found in our study could indicate that the lack of the protective effect of PON1 could be involved in the more severe stages of CHF and is in agreement with the negative correlation between PON1 activity and severity of heart failure." (PMID 33167963, 2020).
type 1 diabetes (14 papers, 2012 to 2025). "High apoB-48, low apoE, and a decrease in PON-1 activity (anti-oxidative capacity of HDL) together with impaired AIx response suggest that patients with type 1 diabetes are likely at higher risk of vascular dysfunction and cardiovascular disease." (PMID 24959195, 2014). "We also found that after a high-fat meal, individuals with type 1 diabetes were unable to decrease the augmentation index and had a decreased activity of an antioxidant enzyme, paraoxonase (PON-1)." (PMID 36619534, 2022). "In response to high-fat meals, early signs of vascular dysfunction alongside accumulation of chylomicron remnants, higher augmentation index, and decreased PON-1 activity were observed in patients with type 1 diabetes." (PMID 24959195, 2014). "Increased oxidative stress and altered antioxidant-protective mechanisms reported in type 1 diabetic animal models can lead to reduced PON1 due to inhibition of the enzyme by its substrates, lipid peroxides." (PMID 23691522, 2013). "For example, we have recently shown that HDL-associated PON1, an enzyme with athero-protective properties, is positively correlated with medium-sized HDL-P and protection from vascular complications in subjects with type 1 diabetes." (PMID 37100172, 2023). "The activities of the HDL-associated enzymes PLTP (p < 0.001), and CETP (p = 0.007) were higher and paraoxonase (PON-1) activity, an anti-oxidative enzyme bound to HDL, decreased in patients with type 1 diabetes (p = 0.027)." (PMID 24959195, 2014).
colorectal cancer (13 papers, 2007 to 2024). A primary or metastatic malignant neoplasm that affects the colon or rectum. "Its diagnostic value in colorectal cancer has been reported, but the diagnostic value of combining PON1 with carcinoembryonic antigen (CEA), carbohydrate antigen 19-9 (CA19-9), carbohydrate antigen 12-5 (CA12-5) in colorectal cancer has not been evaluated." (PMID 33046970, 2020). "Finally, this study is a retrospective study that requires further design of a prospective study to demonstrate that PON1 combined with tumor biomarkers can improve the diagnostic efficacy of colorectal cancer." (PMID 33046970, 2020). "Some patients experienced a further decline in PON1 by Day 21, which may be associated with other comorbidities, late stage colorectal cancer and complications." (PMID 31234489, 2019). "Our findings show that baseline PON1 activity is lower in colorectal cancer patients and significant reductions are observed in the acute inflammatory state post-surgery." (PMID 31234489, 2019). "The activity of PON1 enzyme was shown to be low in 50 Egyptian patients with colorectal cancer but with significant increases one month post-surgery; similar to 49 French patients with BC recurrence." (PMID 29176871, 2017). "Moreover, PON1 activity is elevated in the serum of patients with colorectal cancer and tissues of patients with colon cancer." (PMID 34819088, 2021). "Therefore, this study focused on the plasma PON1 levels in Chinese population and the value of PON1 combined with tumor biomarkers in the diagnosis of colorectal cancer." (PMID 33046970, 2020). "Additionally, an increase in the histone deacetylase activity that accompanied the decrease of PON1 activity observed in colorectal cancer progression suggested that histone deacetylase contributes to the loss of PON1 activity during cancer development, but the exact mechanism is yet unclear." (PMID 36833509, 2023). "A few DEPs have been previously reported as molecules connected with response to RT in colorectal cancer, including FGB, CD44, GLUT1/SLC2A1, PON1." (PMID 35205741, 2022). "Our study assesses the effects of acute inflammation on PON1 and HDL subclasses in post-surgical colorectal cancer patients." (PMID 31234489, 2019). "Other investigators have not reported any significant differences in PON1 genotype distributions in patients with colorectal cancer comparison to healthy individuals." (PMID 17362500, 2007).
systemic lupus erythematosus (13 papers, 2011 to 2024). An autoimmune multi-organ disease typically associated with vasculopathy and autoantibody production. "They showed decreased PON1 activity in lupus subjects, which was associated with clinical atherothrombotic complications (p < 0.01)." (PMID 36118876, 2022). "In patients with systemic lupus erythematosus (SLE) the risk of lupus nephritis was associated with three SNPs in the PON1 promoter region (-1074 A/G, -160 G/A, and -107 C/T)." (PMID 33670025, 2021). "Elevated anti-apoA1 antibody titers are correlated with an increase in Systemic Lupus Erythematosus Disease Activity Index (SLEDAI) and are inversely proportional to PON1 activity." (PMID 39574464, 2024). "PON1 activity is reportedly lower in subjects with systemic lupus erythematosus (SLE)." (PMID 22685667, 2012). "Furthermore, impaired PON1 activity and elevated MPO levels were reported in systemic lupus erythematosus (SLE)." (PMID 36671490, 2023).
acute coronary syndrome (12 papers, 2012 to 2024). Signs and symptoms related to acute ischemia of the myocardium secondary to coronary artery disease. "Low CEC was associated with a higher likelihood of developing acute coronary syndrome when antioxidative activity (reflected in paraoxonase 1 activity) was also low." (PMID 37509557, 2023). "This genotype distribution determines more than 2-fold higher risk of developing acute coronary syndrome when an individual is a carrier of genotypes with the variant M allele of PON1 L55M." (PMID 36547064, 2022). "The results of our current study suggest that the variant M allele and the M allele genotypes (LM + MM) of the PON1 L55M polymorphism are risk factors for acute coronary syndrome, especially for patients with STEMI." (PMID 36547064, 2022). "The objective of our study is to verify if PON1 55 polymorphism is associated with risk of acute coronary syndrome (ACS) and with biochemical myocardial ischemia markers, such as troponin I, creatine kinase (CK)-MB, myoglobin, and C-reactive protein." (PMID 22536511, 2012). "Accordingly, the main aim of our study was to investigate the relationship between the PON1 55 polymorphism and acute coronary syndrome in elderly patients." (PMID 22536511, 2012). "The results of the genotyping for PON1 L55M (163T > A, rs 854560) SNP showed a statistically significant difference (p = 0.023) between the controls and the whole group of patients with acute coronary syndrome." (PMID 36547064, 2022). "Our study aimed to analyze the cholesterol efflux capacity and antioxidative activity (as reflected in Paraoxonase 1(PON1) activity) of HDL in patients of acute coronary syndrome." (PMID 32293456, 2020). "The purpose of this study is to better explore this issue analysing the relationship between PON1 55 polymorphism and ACS (acute coronary syndrome)." (PMID 22536511, 2012). "The objective of this study is to explore the relationships of the effects of CYP2C19 and PON1 Q192R polymorphism on the activity of clopidogrel and the risk of high platelet responsiveness (HPR) by thrombelastography in patients with acute coronary syndrome (ACS)." (PMID 31772608, 2019). "When combined with atorvastatin in acute coronary syndrome, probucol appears to lower oxidized LDL and paraoxonase-1 beyond those achieved with statin alone." (PMID 26512646, 2015).
Cognitive impairment (12 papers, 2013 to 2025). Abnormal cognition is characterized by deficits in thinking, reasoning, or remembering. "Taken together, these findings identify PON1 as a new factor associated with impaired cognition in MCI." (PMID 37175471, 2023). "In patients with mild cognitive impairment, PON1 activity predicted global cognition, verbal episodic memory, and attention/processing speed." (PMID 37175471, 2023). "Overall, through its anti-inflammatory properties, PON-1 and the other PON enzymes may serve a protective role against prolonged neuroinflammation that leads to adverse outcomes, such as cognitive impairment, reduced plasticity, and neuronal damage." (PMID 37108044, 2023).
Hepatic steatosis (12 papers, 2016 to 2025). Steatosis is a term used to denote lipid accumulation within hepatocytes. "Furthermore, PON1 deficiency is associated with oxidative stress and metabolic alterations, leading to liver steatosis in mice fed with a high-fat, high-cholesterol diet." (PMID 38836837, 2024). "The low PON-1 level in group C may be due to cardiovascular disorders that are associated with rapid growth or fatty liver." (PMID 36356090, 2022). "More relevantly, PON1-deficient mice fed a high-fat high-cholesterol diet showed histological alterations in the liver, suggesting that PON1 plays a major role in protection against oxidative stress on diet-induced fatty liver." (PMID 27642496, 2016). "In experimental investigations employing PON1-deficient murine models, exposure to a high-fat or high-cholesterol diet induced heightened oxidative stress and precipitated perturbations in metabolic processes, ultimately leading to the onset of hepatic steatosis." (PMID 38136158, 2023). "A more recent study has demonstrated that serum PON1 activity is paradoxically maintained in patients with fatty liver index (FLI), above 60, despite low HDL." (PMID 31430977, 2019). "In rats receiving açai, increased serum PON1 activity was correlated with a reduction in hepatic steatosis and hepatic injury." (PMID 27642496, 2016). "The lack of influence of the rs662 polymorphism on ARE levels among our patients and the relationships between PON1-related parameters, hepatic steatosis, and hepatic ballooning are noteworthy observations that presently lack comprehensive explanations and warrant further scrutiny." (PMID 38136158, 2023). "Moreover, a study using paraoxon as substrate demonstrated that PON1 activity was decreased in patients with hepatic steatosis, as compared with healthy subjects." (PMID 31430977, 2019). "Together, this suggests a potential broad involvement of PON1 in the various histological aspects of MASLD, reinforcing existing evidence connecting PON1 to liver steatosis, inflammation, fibrosis, and general MASLD." (PMID 39334710, 2024). "Based on these findings, we propose that açai has a role in the regulation of PON1 activity and expression, which reduces the production and accumulation of lipoperoxides in LDL, leading to improvement of hepatic steatosis." (PMID 27642496, 2016). "For liver steatosis, the CERS4 rs17160348 TT genotype, PLA2R1 rs3749117 CC genotype, and PLA2R1 rs3749117 CC genotype had significantly higher steatosis proportions than the other 2 genotypes, respectively, while PON1 rs854560 TT genotype had the lower steatosis proportion than the wild genotype." (PMID 38836837, 2024).
Parkinson disease (12 papers, 2010 to 2025). A progressive degenerative disorder of the central nervous system characterized by loss of dopamine producing neurons in the substantia nigra and the presence of Lewy bodies in the substantia nigra and locus coeruleus. "Paraoxonase 1 (Pon1) is a protein associated with AD, Parkinson's disease and other brain disorders." (PMID 37335084, 2023). "The polymorphism of the PON1 C-108T promoter region and the AChE deletion (ΔAChE) were associated with Parkinson’s development by approximately two times." (PMID 33374313, 2020). "The decrease of PON-1 activities has been associated with serum ferritin and transferrin in several diseases, such as Parkinson disease, inflammatory bowel disease, iron deficiency anemia, hereditary hemochromatosis with iron overload, and in beta-thalassemia." (PMID 31366068, 2019). "Although the growing interest in PON1 has been so far focused in cardio-metabolic outcomes, there is evidence that suggests that PON1 genotype and enzyme activity is associated with adult neurological diseases such as Parkinson and Alzheimer48." (PMID 28325913, 2017). "Exposure to organophosphates is associated with lower PON1 activity and has been linked to neurological disorders including AD, Parkinson’s disease (PD), intellectual disability, attention deficit hyperactivity disorder (ADHD), autism, and other developmental neuropathies." (PMID 39125665, 2024). "The involvement of PON1 in neurodegenerative diseases has also been reported; its decreased activity is associated with ischemic stroke, amyotrophic lateral sclerosis, various types of dementia, Alzheimer’s disease and Parkinson’s disease." (PMID 36833509, 2023). "In the case of Parkinson’s disease, it is the accumulating dopaminergic neurotoxin 1-methyl-4-phenyl-tetrahydropyridine of the chemical structure, similar to OPs, which interacts with PON1." (PMID 36833509, 2023). "The authors suggested that hereditary interaction at the AChE and PON1 locus may increase the occurrence of insecticide-induced Parkinson’s disease." (PMID 33374313, 2020).